BNIP3 (BCL2 interacting protein 3)
Diseases named in the same sentence as BNIP3 in open-access papers (continued):
Sharing a sentence is not in itself a finding about the gene and the disease.
cardiomyopathy (3 papers, 2015 to 2022). A disease of the heart muscle or myocardium proper. "BNIP3/NIX double cardiac KO mice showed age-dependent mitochondrial abnormalities and cardiomyopathy, suggesting homeostatic roles of mitophagy regulated by BNIP3 and NIX." (PMID 34943839, 2021). "Bnip3 expression is also induced in the heart by pressure overload through a c-Jun-N-terminal kinase (JNK)-FOXO3a pathway and contributes to enhanced cell death and cardiomyopathy by disrupting ER and mitochondrial calcium handling." (PMID 26317696, 2015).
cerebral infarction (3 papers, 2021 to 2022). An ischemic condition of the brain, producing a persistent focal neurological deficit in the area of distribution of the cerebral arteries. "Compared with IR group, NDS, cerebral infarction volume, brain water content, apoptosis rate, and MDA and ROS levels decreased, while SOD, HIF-1α, BNIP3, LC3-II and Beclin-1 levels increased in IL-4 group (P<0.05)." (PMID 36910409, 2022). "2ME2 and IL-4+2ME2 groups had decreased NDS, cerebral infarction volume, brain water content, apoptosis rate and MDA, ROS, HIF-1α, BNIP3, LC3-II and Beclin-1 levels, but increased SOD level compared with those of IL-4 group (P<0.05)." (PMID 36910409, 2022).
endometrial cancer (3 papers, 2022 to 2025). Primary or metastatic malignant neoplasm involving the endometrium (mucous membrane that lines the endometrial cavity). "BNIP3 is high in endometrial cancer tissues, and high levels of BNIP3 are related to postoperative adverse reactions, suggesting that BNIP3 is involved in recurrence." (PMID 35783530, 2022). "Indeed, in type I endometrial carcinoma an upregulation of the mitophagy regulator BCL2‐interacting protein 3 (BNIP3) was observed." (PMID 34606156, 2022).
esophageal squamous cell carcinoma (3 papers, 2014 to 2023). Esophageal squamous cell carcinoma (ESCC) is a type of esophageal carcinoma (EC) that can affect any part of the esophagus, but is usually located in the upper or middle third. "Previous studies reported that BNIP3 knockdown in the esophageal squamous cell carcinoma cell line down‐regulated spontaneous cellular apoptosis." (PMID 32412667, 2020). "Ethyl protocatechuate was reported to induce cell autophagy and apoptosis through the upregulation of BNIP3 and NDRG1 (N-myc downstream-regulated gene-1) in esophageal squamous cell carcinoma cells." (PMID 37057280, 2023).
head and neck cancer (3 papers, 2012 to 2022). A primary or metastatic malignant neoplasm affecting the head and neck. "The functional significance of BNIP3 in cancer cells was first investigated using a single-cell dataset derived from head and neck cancer." (PMID 35912211, 2022).
Hepatitis (3 papers, 2018 to 2022). Inflammation of the liver. "Previous studies showed that overexpressions of Bnip3 and Beclin1 were involved in ConA-induced hepatitis." (PMID 30177931, 2018). "ARC decreased apoptosis and autophagy in ConA-induced hepatitis might also by the inhibition of IL6/Bnip3 pathway." (PMID 30177931, 2018). "IL-6 was also involved in the induction of BNIP3 through the activation of Jak/Stat3 signaling, and the suppression of IL-6/Jaks/Stat3 signaling might contribute to the inhibition of Bnip3-mediated apoptosis and autophagy in ConA-induced hepatitis." (PMID 30177931, 2018). "It has been reported that AG protects against drug-induced hepatitis by suppressing the immune system and regulating autophagy by inhibiting the IFN-γ/IL-6/Stat1 and IL-6/Bnip3 pathways in mice." (PMID 31163644, 2019).
invasive breast carcinoma (3 papers, 2009 to 2022). A carcinoma that infiltrates the breast parenchyma. "Association of BNIP3 mRNA and protein expression with clinicopathological features in invasive breast cancer (n = 40)." (PMID 19505343, 2009). "However, although upregulation of BNIP-3 is associated with good survival outcome in invasive breast carcinoma, it is also linked to an increased risk of recurrence and shorter disease-free survival in DCIS." (PMID 34490076, 2021). "Reduced BNIP-3 expression observed in invasive breast cancer is correlated with poor prognosis characterized by high proliferation and positive lymph node status." (PMID 34490076, 2021). "In 40 cases of invasive breast cancer, BNIP3 mRNA in situ hybridization was performed on frozen sections with a digoxigenin labeled anti-BNIP3 probe." (PMID 19505343, 2009). "In the present study we have investigated the expression of BNIP3 in invasive breast cancer at the mRNA and protein level in correlation with the hypoxic response and clinicopathological features." (PMID 19505343, 2009). "To test the hypoxic response in invasive breast carcinomas in relation to BNIP3, we also examined the expression of HIF-1α and its target genes Glut-1 and CAIX." (PMID 19505343, 2009). "The aim of the present study was to investigate the expression of BNIP3 in invasive breast cancer at the mRNA and protein level in correlation with the hypoxic response and clinicopathological features." (PMID 19505343, 2009). "Little is known about BNIP3 expression in invasive breast cancer." (PMID 19505343, 2009). "There are therefore no firm clues that BNIP3 expression in invasive breast cancer is hypoxia dependent." (PMID 19505343, 2009).
legionellosis (3 papers, 2017 to 2024). Any disease caused by Legionella bacteria. "Although BNIP3 and BCL-RAMBO do not influence Legionella infection, alternate regulators of mitochondria-mediated cell death signaling may be targeted by Legionella to promote bacterial replication or egress." (PMID 28261564, 2017).
mitochondrial DNA depletion syndrome 13 (3 papers, 2024 to 2025). Any mitochondrial DNA depletion syndrome in which the cause of the disease is a mutation in the FBXL4 gene. "FBXL4 loss-of-function mutations lead to excessive BNIP3/3L-dependent mitophagy, thereby causing a devastating multi-system disorder called mitochondrial DNA depletion syndrome, type 13 (MTDPS13)." (PMID 40025034, 2025). "The post-translational regulation of BNIP3L and BNIP3 is disrupted in mitochondrial DNA depletion syndrome 13 (MTDPS13), a multisystem disorder disease caused by variations in the FBXL4 gene." (PMID 40352787, 2025). "The post-translational regulation of BNIP3L and BNIP3 is disrupted in mitochondrial DNA depletion syndrome 13 (MTDPS13), a multi-systemic disorder caused by mutations in the FBXL4 gene and characterized by elevated mitophagy and mitochondrial DNA/mtDNA depletion in patient fibroblasts." (PMID 38423516, 2024).
muscle atrophy (3 papers, 2021 to 2024). The loss of muscle tissue due to inactivity or disease. "Furthermore, their downstream genes such as FBXO32, TRIM63, CTSL, and BNIP3, which have been associated with skeletal muscle atrophy in humans and mice, were found to be significantly upregulated in G. parasuis-infected skeletal muscle." (PMID 38540418, 2024). "In conclusion, this study suggested that BNIP3-denpendent mitophagy was sustained activated at the early stages of remobilization, and it might be one of the causes of the worsening of skeletal muscle atrophy induced by immobilization." (PMID 37542244, 2023). "Many prior works have found increases in BNIP3 during the early phases of muscle atrophy, which then appears to reverse to decreased BNIP3 with prolonged durations (>2 weeks) of disuse." (PMID 34585846, 2021).
pancreatic adenocarcinoma (3 papers, 2009 to 2020). "Indeed, in pancreatic adenocarcinomas, BNIP3 expression was repressed by hypermethylation of the BNIP3 promoter contributing to cancer progression." (PMID 33207677, 2020).
pancreatic ductal adenocarcinoma (3 papers, 2012 to 2019). An infiltrating adenocarcinoma that arises from the epithelial cells of the pancreas. "The expression of BNIP3 has been previously investigated in pancreatic tissues and it was found that this protein is differentially expressed in pancreatic ductal adenocarcinoma, as determined by a combination of microarray and RT-PCR methodologies." (PMID 28968982, 2017). "BNIP3 is downregulated in pancreatic ductal adenocarcinoma and correlates with reduced patient survival." (PMID 22458929, 2012).
periodontitis (3 papers, 2024 to 2025). An acute or chronic inflammatory process that affects the tissues that surround and support the teeth. "The results showed that the six transcriptional biomarkers were closely associated with multiple immune cells in periodontitis samples, particularly TFAP2C, CEBPG, and BNIP3." (PMID 39045324, 2024). "The TFAP2C and BNIP3 transcripts exhibited downregulated expression in the periodontitis group and showed significantly lower expression levels than the control subject." (PMID 39045324, 2024). "The results pertaining to mitophagy-related markers indicated that the expression levels of mitophagy pathway-related genes (Bnip3 and Fundc1) and autophagy-related genes (Map1lc3a and Map1lc3b) were significantly upregulated in the periodontitis+TTM group when compared with the periodontitis group." (PMID 38892077, 2024). "LURAP1L and RGS4 showed significant overexpression, whereas ALOX12B, BNIP3, CEBPG, and TFAP2C were notably underexpressed in periodontitis." (PMID 39045324, 2024). "Secondly, our study identified six transcripts that are tissue biomarkers for periodontitis (ALOX12B, BNIP3, CEBPG, LURAP1L, RGS4, and TFAP2C) potentially significant for periodontitis using three machine learning methods: LASSO, SVM, and RF." (PMID 39045324, 2024). "The results derived from the three machine learning methods were intersected and illustrated in a Venn diagram, revealing six transcriptional biomarkers critical for differentiating periodontitis tissues from healthy tissues: ALOX12B, BNIP3, CEBPG, LURAP1L, RGS4, and TFAP2C." (PMID 39045324, 2024).
thyroid cancer (3 papers, 2017 to 2024). "This study aimed to investigate the expression and implications of the major autophagy-related molecules light chain (LC) 3A, LC3B, p62, and BNIP-3 in human thyroid carcinoma." (PMID 28257096, 2017). "Therefore, in this study, we investigated the expression of LC3A, LC3B, p62, and BNIP-3, the major components of autophagy, in human thyroid carcinomas, as well as the implications of these expression patterns." (PMID 28257096, 2017). "In addition, CDH6 was reported to interact with autophagy-related proteins GABA Type A Receptor-Associated Protein (GABARAP), BCL2 Interacting Protein 3 (BNIP3) and BNIP3L to restrict autophagy and to promote the reorganization of the mitochondrial network in thyroid cancer cells." (PMID 31324051, 2019). "We next evaluated the expression of autophagy-related proteins in thyroid cancers and observed significant differences in tumoral LC3A (p < 0.001), stromal LC3A (p < 0.001), LC3B (p < 0.001), and BNIP-3 (p = 0.016) expression patterns with respect to thyroid cancer subtype." (PMID 28257096, 2017).
Anorexia (2 papers, 2010 to 2025). Lack of desire to eat (loss of appetite). "We identified three prognostic genes (EGF, BNIP3, TDGF1) associated with anorexia." (PMID 40495091, 2025).
atherosclerosis (2 papers, 2022 to 2023). A disease characterized by the build-up of fatty material and calcium deposition in the arterial wall resulting in partial or complete occlusion of the arterial lumen. "Although the relationship between HIF signalling and BNIP3 activation is known from carcinogenesis, the role of BNIP3 in context of atherosclerosis has not been described before." (PMID 33913468, 2022).
chronic heart failure (2 papers, 2015 to 2018). "In animal studies, BNIP3 expression was induced by ischemia and upregulated in chronic heart failure or intermittent hypoxic challenge." (PMID 29708992, 2018).
cognitive decline (2 papers, 2021 to 2024). "Genes involved in neuronal postsynaptic density were enriched among DMRs associated with the rate of cognitive decline as measured by mPACCtrailsB, and this enrichment was driven by DMRs annotated to BNIP3, NTRK2, and BAIAP2." (PMID 34654479, 2021). "Given that autophagy is linked to age‐onset neurodegeneration, it is logical that BNIP3 may also reduce the incidence of age‐related cognitive decline." (PMID 38030595, 2024). "The contribution of BNIP3 to cognitive decline has not yet been uncovered, thus it would be interesting to explore its role in cognitive function during healthy and abnormal brain aging." (PMID 38030595, 2024).
COVID-19 (2 papers, 2022). A disease caused by infection with severe acute respiratory syndrome coronavirus 2. "Interestingly, two of these genes, FBXW7 and BNIP3, determine the cell fate via autophagy of mitochondria and apoptosis, implying the important role of mitochondrial functions in COVID-19 severity." (PMID 35547187, 2022). "Similarly, activation of COX2 and HIF-1α in COVID-19 has been shown to upregulate the antiapoptotic antiproliferative microenvironment (BCL2, BNIP3) and M1 immune system {nuclear factor kappa B (NFKB), Egl-9 family hypoxia inducible factor 3 (EGLN3), CXCL8, TNF-α, and IL-6 }." (PMID 36671699, 2022).
dementia (2 papers, 2018 to 2021). Loss of intellectual abilities interfering with an individual's social and occupational functions. "Furthermore, impaired autophagy degradation and inefficient BNIP3-mediated mitophagy may be two possible mechanisms underlying neuronal death during chronic hypoxia, suggesting a potential mechanism for the pathogenesis of CCH-related dementia." (PMID 29459731, 2018).
developmental delay (2 papers, 2014 to 2015). "According to an in silico evaluation, we have suggested that PPP2R2D and BNIP3 losses are likely a cause of developmental delay in the index patient." (PMID 24649379, 2014).
disc degeneration (2 papers, 2024). "We also demonstrated that deletion of mitophagy receptor BNIP3 in NP cells caused mitochondrial dysfunction affecting bioenergetics, triggering meta-inflammation, and resulting in early disc degeneration in mice." (PMID 38464287, 2024). "In summary, hypoxia‐induced BMSC exosomes deliver BNIP3‐rich vesicles to alleviate disc degeneration by activating the mitochondrial BNIP3/ANXA2/TFEB axis, providing a new target for IVDD treatment." (PMID 38973294, 2024).
endometriosis (2 papers, 2024). The growth of functional endometrial tissue in anatomic sites outside the uterine body. "Mechanistically, the mTOR inhibition acts as a hub to activate autophagy mechanisms through increased expression of Beclin1, LC3II, Bnip3, Ambra1, and Parkin in a rat model of endometriosis." (PMID 38645639, 2024). "Although there are several reports on the role of autophagy‐related markers Beclin‐1 and LC3 in endometriosis, only a few studies have exploited in vitro and animal models to study the function of the Bnip3 molecule." (PMID 38645639, 2024). "In a rat model of endometriosis, the expression of mTOR was increased, and the expression of Beclin1, Bnip3, Ambra1, LC3II, and Parkin was decreased, suggesting that the autophagy level is decreased in ectopic endometrium compared to eutopic endometrium and normal endometrium." (PMID 38645639, 2024).
epilepsy (2 papers, 2024). A brain disorder characterized by episodes of abnormally increased neuronal discharge resulting in transient episodes of sensory or motor neurological dysfunction, or psychic dysfunction. "The functional impact of BNIP3-mediated autophagy differs according to the cell type and context, but it is evidently implicated in the pathogenesis of epilepsy." (PMID 40217519, 2024). "The neuroprotective effect of TRPM2 knockout could decrease neuronal apoptosis via PARP‐1/BNIP3/AIF in epilepsy." (PMID 38801174, 2024). "In PTZ-induced epileptic models, the knock-out of TRPM2 has shown efficacy in ameliorating epilepsy-induced hippocampal pathological damages, probably via the PARP1 downstream signaling pathway involving BNIP3." (PMID 40217519, 2024).
head and neck squamous cell carcinoma (2 papers, 2021 to 2025). A squamous cell carcinoma that arises from any of the following anatomic sites: lip and oral cavity, nasal cavity, paranasal sinuses, pharynx, larynx, and salivary glands. "UALCAN assessed BNIP3 expression in patients with head and neck squamous cell carcinoma." (PMID 39945227, 2025).
hypoxic-ischemic-encephalopathy (2 papers, 2020 to 2021). "DIM also downregulated the mRNA expression of HIF1A-regulated Bnip3 and Hif1a which is a hypoxic marker, and the expression of miR-181b which is an indicator of perinatal asphyxia." (PMID 32816128, 2020). "In relation to BCL2L2, BNIP3 (FC = 1.17, p = 0.04) encodes BCL2 interacting protein 3, which is increased in hypoxic-ischemic-encephalopathy and physiological ageing, and has been shown to increase in association with cellular senescence especially in cells over-expressing p21 and p16." (PMID 33964983, 2021).
injury (2 papers, 2023 to 2024). Damage inflicted on the body as the direct or indirect result of an external force, with or without disruption of structural continuity. "In the lung, activation of BNIP3 can result in necrotic cell death in lung epithelial cells, contributing to the progression of severe lung diseases, such as acute lung injury and acute respiratory distress syndrome (ARDS)." (PMID 38540059, 2024).
intellectual disabilities (2 papers, 2015 to 2021). "The gene–disease analysis further revealed that the ATP6V1A/BNIP3 and CAMK4/TIPRL/TOMM70 signatures were associated with several brain-related disorders, including developmental disabilities, schizophrenia, intellectual disabilities, abnormal cerebral white matter morphology, and mental retardation." (PMID 34683848, 2021).
ischemia reperfusion injury (2 papers, 2024 to 2026). Adverse functional, metabolic, or structural changes in ischemic tissues resulting from the restoration of blood flow to the tissue (reperfusion), including swelling; hemorrhage; necrosis; and damage from free radicals. "The HIF-1α/BNIP3 axis protects the kidney from ischemia-reperfusion injury (IRI) by promoting ER autophagy (reticulophagy)." (PMID 41602837, 2026).
laryngeal carcinoma (2 papers, 2012 to 2021). Carcinoma that arises from the laryngeal epithelium. "In addition to FUNDC1, which mediates oxidative stress-induced mitophagy in laryngeal cancer cells, BNIP3 is also involved in the regulation of mitophagy in cancer cells." (PMID 33879840, 2021).
liver fibrosis (2 papers, 2025). "Loss of myeloid XBP1 impairs BNIP3‐mediated mitophagy and promotes macrophage cGAS/STING/NLRP3 activation through leakage of mtDNA into the cytosol, thereby exacerbating liver fibrosis." (PMID 40211890, 2025). "BNIP3-mediated mitophagy inhibition exacerbates liver fibrosis." (PMID 41438738, 2025).
metabolic syndrome (2 papers, 2025 to 2026). A cluster of metabolic risk factors for CARDIOVASCULAR DISEASES and TYPE 2 DIABETES MELLITUS. "Moreover, mitophagy, via PINK1/Parkin or BNIP3-dependent pathways, maintains mitochondrial integrity and restrains inflammation; impaired mitophagy, particularly in the context of metabolic syndrome, may blunt the efficacy of conditioning." (PMID 40885749, 2025).